INS (insulin)
Diseases named in the same sentence as INS in open-access papers (continued):
Sharing a sentence is not in itself a finding about the gene and the disease.
diabetes (continued). "The omentin expression may be affected by insulin and glucose levels in different types of diabetes more than fat-mass, and due to the local activity, the serum omentin may not comply with its gene expression." (PMID 31428203, 2019). "Residents may be dependent on care home staff in relation to interventions around diabetes management, particularly with tasks such as blood glucose monitoring or insulin injections." (PMID 31008705, 2019). "Diabetes may either prevent the pancreas from producing insulin or prevent the body cells from responding to insulin properly." (PMID 31878195, 2019). "Inflammation enhances the progression of diabetes by decreasing peripheral insulin sensitivity." (PMID 31915456, 2019). "Acute exercise increases glucose uptake, promotes mitochondrial biogenesis, and enhances insulin sensitivity, consequently regular physical exercise is recommended for the treatment and prevention of chronic conditions/diseases including obesity and diabetes." (PMID 31686269, 2019). "Currently, there are various drugs used to treat diabetes mellitus, including insulin secretagogues, insulin sensitizer, α-glucosidase inhibitor, insulin, or insulin analogues, dipeptidyl peptidase-4 (DPP-4) inhibitor, glucagon-like peptide-1 (GLP-1) analogues, and other oral antidiabetic drugs." (PMID 31950036, 2019). "Insulin is susceptible to glycation by glucose, d-ribose, and other highly reactive carbonyls, such as methylglyoxal, especially in diabetic conditions, and the AGE products are considered to be the main cause of diabetes-related vascular complications." (PMID 31035509, 2019). "Patients with most advanced diabetes may need an additional treatment such as rapid acting insulin (RAI) on top of basal insulin." (PMID 31023374, 2019). "To investigate whether the alteration of IRS1 through Ser phosphorylation is associated with type 1 diabetes mellitus (T1DM)-induced memory deficits, we generated STZ-induced insulin-deficient T1DM mice." (PMID 31426549, 2019). "As our data show that this maintains glucose-stimulated insulin secretion, targeting Nrf2 might be suited to ameliorate progression of type 2 diabetes mellitus." (PMID 31827698, 2019). "Traditional methods of treating diabetes include burdensome daily insulin-sensitizing drugs or insulin injection, which can only alleviate symptoms of hyperglycemia, but cannot maintain normaglycemia continually and thus fail to fundamentally cure diabetes." (PMID 31885612, 2019). "With the obesity-T2D symbiosis in mind, it seems therapeutically counterproductive that many of the available anti-diabetes medications (especially insulin for advanced patients) lead to weight gain rather than loss." (PMID 31156558, 2019). "In a clustering analysis of the ADOPT and RECORD (Rosiglitazone Evaluated for Cardiac Outcomes and Regulation of Glycaemia in Diabetes) studies, the insulin-resistant cluster responded better to thiazolidinediones and the older-patient cluster responded better to sulfonylureas." (PMID 31161345, 2019). "Non-insulin diabetes treatment use before and after insulin initiation." (PMID 30759121, 2019). "We conclude that LDL may mimic the action of insulin in endothelial cells, which might partly explain the increased incidence of diabetes in patients receiving some LDL-lowering therapy." (PMID 30816192, 2019). "In our database 14 out of 39 individuals were considered diabetics (were prescribed oral antidiabetics, insulin or both) at the time of analysis but only one individual (female) showed blood glucose over 6.1 mmol/L (limit to be diagnosed as diabetic) on the sample analyzed." (PMID 30787362, 2019). "Diabetes reduced the total collagen content (∼39%), which was partially restored by insulin therapy (∼53% increase) and completely restored when swimming training was combined with insulin therapy (∼13% increase)." (PMID 31038563, 2019). "More controversial is what to do about the initiation of insulin in patients with diabetes." (PMID 31271255, 2019).
diabetes (continued). "Hyperglycemia and diabetes can also be treated with insulin after surgery, however, using a “sliding scale” with insulin correction is not routinely recommended as it can cause further complications and actually worsen hyperglycemia." (PMID 35240760, 2019). "Supporting a role for diabetes, it has been reported that taller people are more insulin sensitive and have better beta cell function, which might partly be a result of less ectopic fat storage (e.g. in the liver)." (PMID 31501920, 2019). "Nε‐(carboxymethyl) lysine‐conjugated bovine serum albumin is an essential component of advanced glycation end products which could damage mitochondrial functions and result in reducing insulin secretion followed by the incidence of diabetes." (PMID 30474315, 2019). "Involvement of BMPs in glucose metabolism has also been demonstrated in mice with attenuated BMPR1A signaling in β-cells, which lead to decreased expression of key genes involved in insulin gene expression, glucose sensing and diabetes due to impaired insulin secretion." (PMID 30539233, 2019). "It has been demonstrated that diabetes promotes aberrant tau modifications through insulin signaling in humans and animal models, and the prevalent hypothesis is that hyperphosphorylation, and misfolding and fibrillization of tau impair synaptic plasticity." (PMID 30809950, 2019). "Ivacaftor treatment was demonstrated to improve exocrine pancreatic function as well as insulin secretion profile, which may alleviate or even reverse CF-related diabetes." (PMID 32153386, 2019). "Randomized controlled trials showed that dietary magnesium supplementation reduces plasma glucose concentrations in patients with pre-diabetes and hypomagnesemia, and improves insulin sensitivity, fasting glucose concentrations, and HbA1c concentrations in patients with type 2 diabetes mellitus." (PMID 30813254, 2019). "Physical activity intervention in sedentary individuals with obesity and type 2 diabetes mellitus improves mitochondrial content and insulin sensitivity in skeletal muscle, and especially when combined with moderate weight loss substantially improves lipotoxicity." (PMID 30811418, 2019). "Diabetes mellitus (DM) is a severe metabolic disorder of multiple etiologies characterized by chronic hyperglycemia with disturbances of carbohydrate, lipid, and protein metabolism, resulting in defects in the action of insulin secretion." (PMID 31466303, 2019). "Insulin under dosing can drive to hyperglycemia (BG > 180 mg/dl) and eventually life-threatening short-term complications, such as diabetes ketoacidosis, or long-term complications such as cardiovascular diseases, kidney disease, retinopathy, neurological damage and diabetic foot." (PMID 30922295, 2019). "Similarly, the United Kingdom Prospective Diabetes Study (UKPDS) showed that the progressive nature of diabetes is that the function of β-cells continues to decrease while insulin sensitivity remains unchanged in people recently diagnosed with T2DM." (PMID 31772943, 2019). "Therefore, in addition to the correct way of insulin delivery, structured and regular diabetes education is a cornerstone of the successful management of diabetes mellitus." (PMID 30901914, 2019). "Also, several changes were implemented during this period in diabetes care, practice and management, through introduction of novel fast acting insulin formulations, intensive insulin treatment and educational interventions." (PMID 30932298, 2019). "Our fly diabetes models mimic most closely diabetes mellitus type II, or resistance to insulin." (PMID 30805360, 2019). "Continuous IV recombinant human insulin infusion in combination with haemodiafiltration could be an option for the treatment of severe DKA in patients with diabetes with insulin allergy." (PMID 31711488, 2019).
diabetes (continued). "Sulfonylureas and insulin analogues, which are commonly used as second- and third-line therapies for diabetes, may lead to increased insulinlike growth factor levels and hence promote prostate cancer growth and simultaneously increase PSA levels." (PMID 31693126, 2019). "Interestingly, Alk3 deletion leads to diabetes due to impaired insulin secretion and to a decreased expression of genes involved in insulin gene expression." (PMID 30539233, 2019). "The guidelines for treatment and management of diabetes in Bangladesh follows lifestyle management as the first line care, metformin as second line care and then insulin, etc. depending on the health requirement (presence of comorbidity and complications) of the patients." (PMID 31455307, 2019). "I take my diabetes medication (e. g. insulin, tablets) as prescribed." (PMID 31938590, 2019). "Diabetes is a bihormonal disorder resulting from combined insulin and glucagon secretion defects." (PMID 30415925, 2019). "Although research suggests diabetes is associated with increased postoperative morbidity after hip and knee replacement, the effect of diabetes and varying management with insulin versus non-insulin agents on TSAs is not established." (PMID 30621737, 2019). "Moreover, the significant efficiency of the tested compounds with respect to raising SIL, implies that the insulin-secretagogue activity is amongst diabetes controlling mechanisms of AS, FKCA, and KRA." (PMID 31143690, 2019). "Here we utilized the ethologically relevant Novel Object Recognition (NOR) test to verify that STZ-diabetic rats develop diabetes-associated cognitive deficits and investigate the effect of insulin treatment." (PMID 31451429, 2019). "Though the level of insulin was not assessed in this work, probably, the lack of insulin in the condition of diabetes is the cause of elevation in triglycerides and cholesterol." (PMID 31828075, 2019). "In these patients diabetes mellitus is resistant to ketosis, maybe because of their endogenous hyperinsulinaemia and some of them need very high doses of insulin to control glycaemia, up to 3,000 units per day." (PMID 31214120, 2019). "Although in recent years, we have seen increased interest in applying machine learning methodologies in the study of personalize diabetes treatment planning, this study is the first of its kind that aims at finding the best insulin dosage for the T1DM for several reasons." (PMID 31464196, 2019). "In addition to impaired peripheral and central insulin signaling seen in diabetes models, impaired memory function in Alzheimer’s disease (AD) is associated with disrupted brain IR signaling." (PMID 31057368, 2019). "Insulin aggregation is a crucial factor in the development of diabetes." (PMID 31018524, 2019). "Consistent with our results, Sampath reported that TRX may play a significant role in the management of type 2 diabetes mellitus by improving insulin signaling molecules, including the SRC, Akt and GLUT4 proteins." (PMID 31182097, 2019). "Glucocorticoids impair both insulin secretion and insulin sensitivity, and over time contribute to the failure of beta-cells to adequately enhance insulin secretion compensating for the increased insulin resistance, and therefore to the development of diabetes." (PMID 30467627, 2019). "Taken these finding, it is concluded that A. esculentus treatment can improve body weight reduction and insulin resistance indices of diet induced diabetic animals, supporting that okra may be useful in the treatment of diabetes." (PMID 31089371, 2019). "Similarly, the B1R agonist des-Arg9-bradykinin can induce the release of insulin and increase pancreatic vascular permeability, suggesting an important role for B1R in the pathophysiology of diabetes and related diseases such as AD." (PMID 31632239, 2019). "Similarly, her son (F1957-III-1) also has been requiring insulin (30 U/day) therapy for 5 years since he was diagnosed with diabetes at the age of 26." (PMID 31143779, 2019).
diabetes (continued). "Interestingly, dysfunction or inhibition of some specific genes such as Ide, Ppp1r3c, Hdac9, Ghsr and Gckr can improve insulin sensitivity to varying degrees in pre-diabetes period in GK rats." (PMID 30687391, 2018). "The loss of statistical significance after adjusting for potential confounders could be due to the rather small number (n = 45) of insulin-resistant individuals among our participants, also preventing our analyses to extend to diabetes prevalence." (PMID 30477276, 2018). "Innovation in drug research and development and the use of insulin could not substitute for the role of lifestyle interventions in improving diabetes control; conversely, a long-term poor lifestyle had adverse effects on drug and insulin therapy." (PMID 30541544, 2018). "Diabetes mellitus is a multiple-etiology metabolic disorder characterized by chronic hyperglycemia, with alterations in carbohydrate, fat, and protein metabolism due to defects in secretion and/or insulin action." (PMID 30274207, 2018). "Although metformin benefits patients with diabetes by improving insulin sensitivity, whether it increases insulin secretion, particularly during the first phase of secretion, remains unclear." (PMID 29482528, 2018). "We hypothesized that a calorie-restricted diet, high in fiber and coffee, but free of red meat, according to the German Diabetes Risk Score (GDRS), improves beta-cell function as assessed by insulin secretion in patients with T2D." (PMID 30619502, 2018). "Their study also showed that OC might improve glucose metabolism through enhancing insulin secretion in both males and females and by improving insulin resistance in females with type 2 diabetes mellitus." (PMID 30428526, 2018). "In addition, the concept of being “on-board” was widely treated in diabetes research related to the insulin effect." (PMID 30363935, 2018). "The possible relationship between the decrease of LncRNA-H19 and the impairment of angiogenesis in diabetes could involve impairment of the insulin–phosphatidylinositol 3-kinase (PI3K)–Akt pathway via the interdiction of LncRNA-H19." (PMID 29334272, 2018). "Associations with the insulin genetic score were assessed in 9437 study participants without diabetes." (PMID 30092829, 2018). "Indeed, our two study groups exhibited similar levels of insulin secretion markers (insulin and C-peptide), whereas people with diabetes exhibited higher glucose and TG levels despite receiving treatment for the disease." (PMID 29467719, 2018). "To that end, we aimed to quantify the impact of OSA on glucose tolerance, insulin sensitivity, beta-cell responsiveness and diabetes risk in a community-based cohort of overweight and obese men and women without diabetes." (PMID 30042734, 2018). "This novel perspective might offer answers to why some previous research therapeutically targeting impaired insulin sensitivity resulted in deleterious effects such as PPARs, including the development of HF in patients with diabetes." (PMID 29440374, 2018). "A total of eight injection devices were identified for non-insulin medications used to treat diabetes: exenatide extended release single-dose tray, exenatide once weekly pen, exenatide twice daily pen, dulaglutide pen, liraglutide pen, albiglutide pen, pramlintide pen, and lixisenatide pen." (PMID 30294713, 2018). "For instance, porcine insulin has been used for treatment of diabetes." (PMID 29370114, 2018). "Inflammation, mitochondrial dysfunction, and ER stress have been proposed to impair insulin sensitivity in diabetes, but the exact mechanisms by which the insulin signaling cascade becomes dysregulated heart function remain unknown." (PMID 30066723, 2018). "Transcriptome profiling and regulatory network analysis indicated that CPAE may ameliorate diabetes through improving β-cell survival and strengthening insulin secretion in the pancreas." (PMID 30140229, 2018).
diabetes (continued). "Furthermore, TEM data demonstrated a significant reduction in autophagosome/autolysosome formation in diabetes patients, strongly supporting a correlation between miR199a-5p/ATG14-mediated autophagy and hepatic insulin sensitivity in diabetes patients." (PMID 29540751, 2018). "Reported side-effects of chronic administration include ulceration of mucosal tissues, haematological abnormalities, induction of insulin insensitivity, obesity, and diabetes, though these adverse effects may be largely dose-dependent." (PMID 30096787, 2018). "However, at the age of 10 months, diabetes remitted and insulin injections were discontinued by the mother, before initiating the scheduled sulfonylurea treatment protocol." (PMID 28943514, 2018). "Pathophysiological manifestations of diabetes, i.e., increased plasma glucose, insulin, AGEs and free fatty acids, enhanced reactive oxygen species (ROS), and oxidative stress, and increased DNA damage, have been reported to be considerably higher in people with poor glycemic control, and diabetes." (PMID 30002281, 2018). "This included 016 who described picking up “handy tricks” from his peers at a diabetes camp he attended soon after starting to use an insulin pump: “cause this pump, I had only had it not that long." (PMID 29961962, 2018). "Although patient numbers were small and SAEs were infrequent, this suggests patients with diabetes with worse nausea or early satiety may need more aggressive surveillance while adopting intensive insulin therapies." (PMID 29652893, 2018). "The association between severe hypoglycaemia and all-cause mortality was maintained after adjustment for the following baseline characteristics: age, sex, HbA1c, BMI, diabetes duration, insulin regimen, hepatic impairment, renal status and cardiovascular risk group." (PMID 28913543, 2018). "With the exception of a brief comment on insulin-activity timing, as of 2018 no information regarding exercise-drug timing is currently provided in the ADA guidelines for preventing and treating T2DM." (PMID 30061841, 2018). "The T2DM participants were taking diabetes medications at the time of the study that varied in their nature, and it is possible that these different medications affected their insulin and C-peptide responses in the MTT, especially in the patients with a sulphonylurea." (PMID 29791512, 2018). "In addition, this review and analysis were conducted only among persons using glucose-lowering drugs and/or insulin, as those are the published studies in diabetes with cognitive outcomes." (PMID 29387262, 2018). "During diabetes there is a high occurrence of apoptosis in lymphocytes and insulin treatment reduces this effect, suggesting that insulin may act as a pro-survival factor for lymphocytes." (PMID 29867762, 2018). "Of note, in the larger of these two studies, depression remission was positively associated with only one of three diabetes outcomes examined (insulin level after a glucose challenge, but not fasting insulin or glucose levels)." (PMID 30138433, 2018). "Although some evidence supports the inverse relation between Δ5-desaturase activity and diabetes risk, the Δ5-desaturase activity of this study did not correlate to insulin and HOMA-IR, which are risk factors of type 2 diabetes." (PMID 29471812, 2018). "Finally, patients treated with insulin or oral hypoglycemic agents probably had diabetes even though FPG or 2-hour OGTT levels were within the normal range." (PMID 29951547, 2018). "Insulin is a frequently used therapeutic agent in the management of diabetes mellitus." (PMID 30344288, 2018). "Thus, fasting people with diabetes have lower levels of osteocalcin, higher levels of glucose and lower levels of insulin." (PMID 30057568, 2018).